RNU6-1023P (RNA, U6 small nuclear 1023, pseudogene)
Gene: Small nuclear RNA gene on chromosome 6 (54,786,387 to 54,786,492, forward strand). Ensembl gene ENSG00000251946.
Homologues: Orthologues: chimpanzee U6 (97% identical), macaque U6 (89% identical), mouse Gm26371 (73% identical). Paralogues in human: RNU6-698P (80% identical), RNU6-1260P (79% identical), RNU6-1125P (78% identical), RNU6-207P (78% identical), RNU6-21P (78% identical), RNU6-38P (78% identical), RNU6-42P (78% identical), RNU6-468P (78% identical), RNU6-774P (78% identical), RNU6-890P (78% identical), RNU6-891P (78% identical), RNU6-1067P (77% identical), and 1286 more.